RCAN1 (regulator of calcineurin 1)
Diseases named in the same sentence as RCAN1 in open-access papers (continued):
Sharing a sentence is not in itself a finding about the gene and the disease.
cardiac hypertrophy (21 papers, 2011 to 2024). "An abnormal regulation of RCAN1 gene expression has been associated with cardiac valve development and cardiac hypertrophy, angiogenesis, tumorigenesis and immune system development, and is involved in learning and memory." (PMID 25713607, 2014). "RCAN1 has also been implicated in cardiac valve formation and in inhibition of cardiac hypertrophy." (PMID 21496308, 2011). "To further elucidate the effect of MBT on cardiac hypertrophy, we conducted qRT-PCR experiments to measure the expression of ANP, BNP, β-MHC, and RCAN1 mRNA levels, all of which serve as markers of cardiac hypertrophy." (PMID 38020917, 2023). "For example, Rcan1 expression is driven by and reciprocally regulates calcineurin signaling in cardiac hypertrophy and shows remarkable time-of-day variation in expression." (PMID 36256456, 2022). "Among them, Csrp3, Pdlim5, Sorbs2, Rcan1, and Acta1, which were related to cardiac hypertrophy and remodeling, were upregulated and modified by at least one active histone mark." (PMID 33330655, 2020). "Firstly, RCAN1 has a protective effect on myocardial I/R injury, myocardial hypertrophy and IMH/aortic rupture by modulating mitochondrial function, calcineurin activity and ROCK activity, respectively." (PMID 33267791, 2020). "RCAN1 has been shown to be involved in many physiological and pathological processes, including cardiac valve development, cardiac hypertrophy, inflammation, angiogenesis, cancer and neurodegeneration." (PMID 24751678, 2014). "Accordingly, RCAN1 overexpression in DS cardiac tissue could explain both, the decreased cardiac hypertrophy events and the diminished cardiac injury induced by I/R in DS patients." (PMID 35126461, 2021). "In addition, the beneficial role of RCAN1 reduction in atherosclerosis and the protective role of RCAN1 in myocardial ischemia/reperfusion injury, myocardial hypertrophy and intramural hematoma /aortic rupture are discussed, as well as underlying mechanisms." (PMID 33267791, 2020). "Moreover, weighted gene co-expression network analysis (WGCNA) revealed that the RCAN1 gene is a top hub gene involved in cardiac hypertrophy." (PMID 33267791, 2020). "The RCAN1 protein calcipressin, a calcineurin inhibitor, is shown to be a requirement for extracellular matrix synthesis in cardiac hypertrophy and hepatic fibrosis, two conditions occurring in DS/T21-related hypertrophic cardiomyopathy and autoimmune hepatitis." (PMID 32566271, 2020). "RCAN1 reduction is beneficial to atherosclerosis whereas RCAN1 protects against myocardial ischemia/reperfusion injury, myocardial hypertrophy and intramural hematoma /aortic rupture." (PMID 33267791, 2020). "Expression of Rcan1, which is involved in cardiac hypertrophy, was reduced in the MIC group." (PMID 32756334, 2020). "Enabling vitamin D action in VDR (vitamin D receptor) gene-deleted mice may lead to an increased RCAN1 gene expression and these mice models may display cardiac hypertrophy." (PMID 25713607, 2014). "Therefore, as an endogenous inhibitor of calcineurin, RCAN1 may act against cardiac hypertrophy by regulating calcineurin-dependent pathways." (PMID 33267791, 2020). "For example, the hypomethylation of NFATc2 is predicted to activate RCAN1 and NPPB, which are related to exercise-induced cardiac hypertrophy and concentric hypertrophic cardiomyopathy, respectively." (PMID 38793603, 2024). "While RCAN1 is a physiological inhibitor of NFAT, one of the main pathways involved in cardiac hypertrophy, this molecule also participates in cardiomyocyte protection against I/R injury, probably through mitochondrial dynamic regulation." (PMID 35126461, 2021). "ANP and α-actin are commonly up-regulated in case of cardiac hypertrophy; however, Rcan1 is a reporter of calcineurin–NFAT activation, a well described pathway in cardiac hypertrophy." (PMID 26043922, 2015).
cardiac hypertrophy (continued). "This is not surprising since RCAN1 has been described to play a dual role during the development of cardiac hypertrophy as it can either facilitate or suppress cardiac calcineurin signaling." (PMID 32354146, 2020). "The current study showed a reduced expression of Rcan1 and enhanced cardiac remodeling in the absence of Orai, whereas reduced Rcan1 expression in the absence of TRPC1/TRPC4 led to a decrease in the development of cardiac hypertrophy." (PMID 32354146, 2020).
breast carcinoma (8 papers, 2012 to 2025). "RCAN1 expression in breast cancer tissues is lower than in adjacent healthy tissues, and its isoform RCAN1-4 represses breast cancer progression by inhibiting calcineurin/NFAT2 signaling." (PMID 37107558, 2023). "The survival curves show that in breast cancer, low expression of ETS2 and RCAN1 is associated with a significantly lower probability of survival." (PMID 37107558, 2023). "Pair-wise gene expression correlation analyses revealed that ETS2 and RCAN1 are positively correlated in breast and lung cancers, with a stronger correlation seen in breast cancer." (PMID 37107558, 2023). "Above all, RCAN1 is a tumor suppressor protein, inhibiting tumor growth and tumor angiogenesis in breast cancer." (PMID 35717152, 2022). "RCAN1 has been suggested as a super-enhancer-driven tumor suppressor whose down-regulation enhances the malignant features of breast cancer cells." (PMID 33742056, 2021). "More importantly, our results also supported the functional significance of RCAN1.4-SEdistal in maintaining the malignant phenotype of breast cancer cells." (PMID 32771023, 2020). "We used the CRISPR-Cas9 nuclease system to generate RCAN1.4-SEdistal knockout breast cancer cells with deletion of the ~ 20-kb RCAN1.4 composite enhancer by introduction of a pair of sgRNAs." (PMID 32771023, 2020). "As RCAN1 can be expressed as different mRNA isoforms with different functions, we then detected the breast cancer-specific RNA expression patterns of isoforms of RCAN1 in the ISOexpresso website." (PMID 32771023, 2020). "Here, we identified RCAN1.4, not RCAN1.1 and RCAN1.2, was the major expression isoform of RCAN1 in normal breast tissues and was significantly decreased in breast cancer tissues." (PMID 32771023, 2020). "As expected, ChIP analysis showed a significant association of H3K27ac with the promoter and super-enhancer regions of RCAN1.4 in matched normal breast tissues, which was significantly decreased in the breast cancer tissues." (PMID 32771023, 2020). "Notably, RCAN1 has been reported as a tumor suppressor in many cancers, including thyroid and breast cancers." (PMID 35754026, 2022). "However, the precise regulatory mechanisms and functions of RCAN1 in breast cancer are still unclear." (PMID 32771023, 2020). "Then we further assess the clinical significance of RCAN1 deregulation in breast cancer." (PMID 32771023, 2020). "Therefore, determining the specific role that RCAN1 plays in breast cancer is important for tumour prevention and therapy." (PMID 32771023, 2020). "Therefore, we measured the CaN-NFATc1 signalling in breast cancer cells after stable overexpression or knockout of RCAN1.4." (PMID 32771023, 2020). "Further analysis in the TCGA cohort showed that RCAN1 was decreased in different breast cancer molecular subtypes, indicating that downregulation of RCAN1 was a common event in breast cancer patients." (PMID 32771023, 2020). "In breast cancer, primary HCC, PDAC, colon cancer, ccRCC, and bladder cancer, RCAN1 or RCAN1.4 shows considerably low levels of expression in cancer tissues and results in a poorer prognosis." (PMID 35717152, 2022). "Similar to ETS2, RCAN1 expression was downregulated in luminal and HER2-positive breast cancers compared to TNBC, suggesting that it may influence the molecular features of breast cancer subtypes." (PMID 37107558, 2023). "The UALCAN analyses showed that ETS2 and RCAN1 expressions were not influenced by breast cancer stages." (PMID 37107558, 2023). "Gene expression analyses with GEPIA2 and UALCAN showed that DSCR genes ETS2 and RCAN1 are significantly downregulated in breast and lung cancers, and their expression levels are higher in triple-negative compared to luminal and HER2-positive breast cancers." (PMID 37107558, 2023).
breast carcinoma (continued). "Analysis of breast cancer tissues showed significant downregulation of RCAN1 in comparison with its expression in adjacent non-cancerous tissues from patient samples." (PMID 35717152, 2022). "In addition, we also analysed the prognostic value of combining RCAN1.4 and RUNX3 protein levels in breast cancer samples." (PMID 32771023, 2020). "We identified down-regulation of OXTR, FOS, ITPR1, RCAN1, CAMK2D, CACNA2D and lnc_ZFP161, and up-regulation of lnc_MTX2 in the breast cancer tissues compared with nearby non-cancerous tissues." (PMID 33742056, 2021). "Expression levels of OXTR, FOS, ITPR1, RCAN1, CAMK2D, CACNA2D and lnc_ZFP161 were significantly down-regulated in the breast cancer tissues compared with nearby non-cancerous tissues." (PMID 33742056, 2021). "Expression levels of OXTR, FOS, ITPR1, RCAN1, CAMK2D, CACNA2D and lnc_ZFP161 were significantly down-regulated in breast cancer tissues compared with nearby non-cancerous tissues." (PMID 33742056, 2021).
hepatocellular carcinoma (7 papers, 2020 to 2025). A malignant tumor that arises from hepatocytes. "Previous studies demonstrated that RCAN1 played an inhibitory role in the progression of some gastrointestinal cancers, like hepatocellular carcinoma (HCC), pancreatic carcinoma, and colorectal carcinoma." (PMID 35717152, 2022). "Then the molecular mechanism of GH to induce Rcan1-4 transcription was examined in rat hepatoma H4IIE cells." (PMID 32589657, 2020). "For example, circADAMTS14 suppresses hepatocellular carcinoma (HCC) cell proliferation, invasion, and migration while promoting apoptosis via the miR-572/RCAN1 axis." (PMID 40572671, 2025). "However, Song’s findings showed that circADAMTS14 might limit the progression of hepatocellular carcinoma (HCC) by regulating the endogenous RNA, miR-572/RCAN1." (PMID 36186476, 2022).
atherosclerosis (6 papers, 2013 to 2021). A disease characterized by the build-up of fatty material and calcium deposition in the arterial wall resulting in partial or complete occlusion of the arterial lumen. "Consistent with this view, Rcan1 inactivation in the Apoe-deficient mouse atherosclerosis model attenuates atherosclerotic lesion burden in terms both of lesion area and severity." (PMID 24127415, 2013). "Altered expression of RCAN1 is implicated in the pathogenesis and progress of atherosclerosis." (PMID 33267791, 2020). "RCAN1 has been implicated in important physiological and pathological processes, including atherosclerosis, aneurysm and neointima formation, cardiac hypertrophy, tumor growth, angiogenesis, mast-cell function, T-cell survival, sepsis, and synaptic plasticity and memory." (PMID 30442942, 2018). "As RCAN1 is implicated in cell migration, we investigated its contribution to atherosclerosis." (PMID 24127415, 2013). "In addition, we have identified several mechanisms underlying Rcan1-dependent atherosclerosis development." (PMID 24127415, 2013). "Genetic deletion of Rcan1 significantly reduced the extent and severity of atherosclerosis in ApoE knockout mice with a high-fat diet." (PMID 33267791, 2020). "For example, remarkable increase of RCAN1 was observed in atherosclerosis lesions in patients and mice." (PMID 33267791, 2020). "In the near future, it is desirable to elucidate the RCAN1 function and classify it as a possible biochemical marker to diagnose infancy atherosclerosis." (PMID 25713607, 2014). "Although human and mouse atherosclerosis differ in several aspects, critical features are shared, and our results indicate that one such feature is RCAN1 induction." (PMID 24127415, 2013). "Our results demonstrate that RCAN1 is induced in human and mouse atherosclerosis and strongly suggest that Rcan1 promotes disease progression." (PMID 24127415, 2013). "Moreover, genetic deletion of Rcan1 significantly reduced the extent and severity of atherosclerosis in mice, which directly demonstrated that RCAN1 reduction has beneficial effect on atherosclerosis." (PMID 33267791, 2020). "Current evidence indicates that RCAN1 reduction is beneficial to atherosclerosis, which may have therapeutic potential for slowing or delaying the progression of atherosclerosis by inhibiting CD36 and VEGF signaling." (PMID 33267791, 2020). "It has to be noted that more than a hundred genes are located on chromosome 21, which may contribute to the protective effect on atherosclerosis and hypertension, not only the RCAN1 gene." (PMID 33267791, 2020). "Above evidence suggested that RCAN1 inhibition may have therapeutic potential for slowing the progression of atherosclerosis by inhibiting VEGF-VEGFR2 signaling." (PMID 33267791, 2020). "The inhibition of RCAN1-calcineurin-NFAT pathway by immunosuppressant drugs could lower the atherosclerosis development and maintain the arterial wall integrity." (PMID 25713607, 2014). "Recent studies showed that RCAN1 could be considered a proatherogenic factor and its elucidation may contribute to the diagnosis of infancy atherosclerosis." (PMID 25713607, 2014). "Here, we investigated the contribution of Rcan1 to atherosclerosis development." (PMID 24127415, 2013). "Our data define a major role for haematopoietic Rcan1 in atherosclerosis and suggest that therapies aimed at inhibiting RCAN1 expression or function might significantly reduce atherosclerosis burden." (PMID 24127415, 2013). "We show that RCAN1 is induced in human and mouse atherosclerotic tissues and, using a mouse model of atherosclerosis and bone-marrow (BM) transplantation assays, we demonstrate that Rcan1 in haematopoietic cells promotes atherosclerosis." (PMID 24127415, 2013). "Moreover, RCAN1 reduction protects against atherosclerosis by reducing oxLDL uptake." (PMID 33267791, 2020).
atherosclerosis (continued). "Studies done in knockout mice and macrophages demonstrate the RCAN1 role in the atherosclerosis evolution and results showed that the atherosclerotic plaques have an up-regulate RCAN1 gene expression, meaning that RCAN1 may be considered a proatherogenic factor." (PMID 25713607, 2014). "Constitutive germline genetic ablation of both Rcan1 isoforms in the mouse confers resistance to abdominal AA (AAA), neointima formation, and atherosclerosis progression." (PMID 30442942, 2018). "An up-regulation of RCAN1 gene in endothelium is a result of a thrombin and VEGF activation which can occur in vascular diseases such as atherosclerosis, tumor growth and inflammation." (PMID 25713607, 2014). "Rcan1 regulates CD36 expression and its genetic inactivation reduced atherosclerosis extension and severity in Apoe−/− mice." (PMID 24127415, 2013). "Importantly, no direct evidence shows that RCAN1 plays a beneficial role in hypertension and atherosclerosis." (PMID 33267791, 2020). "The different requirements for BM-cell expression of Rcan1 in atherosclerosis and aneurysm might be attributable to the pivotal role of Rcan1 in foam-cell formation, a central feature of atherosclerosis but not of aneurysm." (PMID 24127415, 2013). "To assess RCAN1 expression in human atherosclerotic lesions, we compared human atherosclerotic coronary arteries with non-atherosclerotic coronary arteries and internal mammary arteries, a vessel that does not develop atherosclerosis." (PMID 24127415, 2013).
diabetes (6 papers, 2019 to 2024). "Similarly, rodent studies have found that overexpression of RCAN1 causes diabetes, age-associated hyperglycemia, impaired glucose tolerance, hypoinsulinemia, loss of β-cells, and the downregulation of key β-cell genes." (PMID 36178378, 2022). "As both stroke and diabetes are age-associated diseases, their role in RCAN1 regulation may also be affected by the aging process." (PMID 32566665, 2020). "Interestingly, mutations in NEUROD1 were associated with T2D, whereas upregulation of RCAN1 was shown to cause hyperinsulinemia, β cell dysfunction, and diabetes." (PMID 31159854, 2019). "Chromosome 21 also encodes other proteins, such as BACE2, RCAN1 and DYRK1A, known to be associated with diabetes mellitus phenotypes and potentially contribute to the increased risk of diabetes mellitus." (PMID 38474215, 2024). "As well as obesity, a number of genes located on the DS critical region of chromosome 21, including dual-specificity tyrosine phosphorylation regulated kinase 1A (DYRK1A) and regulator of calcineurin 1 (RCAN1), are being investigated and are thought to contribute to diabetes in DS." (PMID 36178378, 2022). "Moreover, chronic hyperglycemia, the characteristic of diabetes, increases RCAN1 expression in pancreatic β cells, suggesting that chronic hyperglycemia may also contribute to RCAN1 elevation in the brain." (PMID 32566665, 2020).
heart failure (5 papers, 2017 to 2022). Inability of the heart to pump blood at an adequate rate to meet tissue metabolic requirements. "The RCAN1-4 transcript levels in AS correlated with those of heart-failure signature-molecule brain natriuretic peptide (BNP, encoded by NPPB), indicating that NFAT activation was related to severity of LV stress." (PMID 39086965, 2022). "Pressure-volume loop analysis and RNA expression analysis of Rcan-1, ANP, and BNP as heart failure and hypertrophy markers; Col1a2 as a fibrosis marker; and SERCA2a and PLB as calcium regulatory markers were performed after 4 weeks of administration of 0.2% DS37001789 in TAC mice." (PMID 32055741, 2020).
Huntington disease (5 papers, 2011 to 2023). Huntington disease (HD) is a rare neurodegenerative disorder of the central nervous system characterized by unwanted choreatic movements, behavioral and psychiatric disturbances and dementia. "Comparative transcriptome analysis of longitudinally aged striatal medium spiny neurons (MSNs), a primary neuronal subtype affected in Huntington's disease (HD), identified pathways associated with RCAN1, a negative regulator of calcineurin." (PMID 37214956, 2023).
Hyperglycemia (5 papers, 2016 to 2023). An increased concentration of glucose in the blood. "Thus, our data demonstrated that RCAN1 expression is linked to hyperglycaemia in DS mice, it correlated in islets with a worsening metabolic profile in obese mice, and it is increased in human T2D islets." (PMID 27195491, 2016). "Hyperglycemia suppresses RCAN1 expression in cultured podocytes, which is alleviated by pretreatment with the DNA methyltransferase inhibitor 5-Aza-2’-deoxycytidine." (PMID 36618403, 2022). "Mechanistically, increased expression of RCAN1 decreased hyperglycemia-induced nuclear factor of activated T cells (NFAT) transcriptional activity." (PMID 36618403, 2022). "This approach produced a single gene, RCAN1, as a candidate gene linking hyperglycemia and functional changes in T2D β-cells." (PMID 27195491, 2016). "Some studies found that the acute induction of RCAN1 by increased reactive oxygen species and hyperglycemia could inhibit endocrine cell apoptosis and protect them from damage." (PMID 36901708, 2023).
Obesity (5 papers, 2019 to 2022). Accumulation of substantial excess body fat. "Therefore, it will be of interest to determine whether regulating CaN signalling via upstream control of CaM availability would have a similar impact on diet-induced obesity and glucose handling as those observed with other endogenous regulators of CaN, such as RCAN1." (PMID 32033037, 2020). "Rcan1-null mice also had increased expression of uncoupling protein 1 (UCP-1) in adipose tissue, which is a mitochondrial uncoupler well-known to have implications for diet-induced obesity." (PMID 32033037, 2020).